ABCA10 (ATP binding cassette subfamily A member 10)
Description:
Probable transporter which may play a role in macrophage lipid transport and homeostasis.
Synonyms: EST698739
Tractability: Antibody: UniProt predicts a signal peptide or a membrane-spanning region; its Gene Ontology location is reachable by antibodies, with medium confidence.
Gene: Protein-coding gene on chromosome 17 (69,147,214 to 69,244,846, reverse strand). Ensembl gene ENSG00000154263.
Subcellular location: Membrane
Pathways (Reactome):
Transport of small molecules: ABC transporters in lipid homeostasis
Gene Ontology:
Molecular function: ATPase-coupled transmembrane transporter activity; ABC-type transporter activity; ATP binding; ATP hydrolysis activity
Biological process: lipid transport; transmembrane transport
Cellular component: membrane; plasma membrane
Genetic constraint (gnomAD): Loss-of-function variants: 139 observed, 153.31 expected, observed/expected ratio (o/e) 0.91, 90% interval 0.79 to 1.04. The upper end of that interval is the gene's LOEUF score, 1.04, which puts it in group 4 of 6, group 1 being the genes least tolerant of losing a copy. Missense variants: 1,526 observed, 1,632.6 expected, observed/expected ratio (o/e) 0.93, 90% interval 0.89 to 0.98. Synonymous variants: 523 observed, 550.39 expected, observed/expected ratio (o/e) 0.95, 90% interval 0.88 to 1.02.
Homologues: Orthologues: chimpanzee ABCA10 (96% identical), tropical clawed frog abca10 (45% identical), zebrafish abca5 (42% identical), Drosophila melanogaster Abca3 (23% identical), Caenorhabditis elegans abt-4 (23% identical), Drosophila melanogaster CG6052 (22% identical), Caenorhabditis elegans abt-2 (22% identical), Drosophila melanogaster CG31213 (21% identical), Drosophila melanogaster ldd (20% identical), Drosophila melanogaster CG8908 (20% identical), Drosophila melanogaster Eato (19% identical), Drosophila melanogaster CG1494 (18% identical), and 6 more. Paralogues in human: ABCA9 (62% identical), ABCA6 (62% identical), ABCA8 (61% identical), ABCA5 (43% identical), ABCA1 (26% identical), ABCA7 (26% identical), ABCA2 (26% identical), ABCA3 (25% identical), ABCA13 (25% identical), ABCA12 (25% identical), ABCA4 (25% identical).
Diseases named in the same sentence as ABCA10 in open-access papers:
ABCA10 is named in the same sentence as 22 diseases in open-access papers, as found by Europe PMC text mining. Sharing a sentence is not in itself a finding about the gene and the disease. The quoted sentences say what the papers report.
breast carcinoma (4 papers, 2022 to 2025). "We evaluated the potential correlation between ABCA10 expression in breast cancer and several mutations commonly seen in breast cancer." (PMID 35247251, 2022). "We demonstrate the expression of different ABCA10 modulators in breast cancer associated with genetic variants, deletions, tumor mutation burden (TMB) and TME." (PMID 35247251, 2022). "Mutations in ABCA10 are positively associated with different immune cells in six different immune databases and play an important role in immune cell infiltration in breast cancer." (PMID 35247251, 2022). "We also demonstrated that the ABCA10 signature was associated with immunotherapeutic response and poor prognosis in a breast cancer cohort." (PMID 35247251, 2022). "The Kaplan-Meier prognostic survival curve analysis showed that the high expression of ABCA10 gene in breast cancer tissues indicates a good prognosis." (PMID 35247251, 2022). "Although we have tested the expression of ABCA10 in various breast cancer cell lines and confirmed the same as predicted, ABCA10 deserves further study to become a new breast cancer tumor marker." (PMID 35247251, 2022). "Subsequently, results in different breast cancer subtypes also showed higher expression of ABCA10 in normal tissues than in other subtypes." (PMID 35247251, 2022). "Strikingly, only 20 of the 84 breast cancer cell lines were dependent on ABCA10 levels, suggesting that both clinical patients and breast cancer cells are sufficient to show that ABCA10 levels are low in the development of breast cancer." (PMID 35247251, 2022). "After analysis through the ONCOMINE database, we found that ABCA10 levels were much lower than normal tissues only in breast cancer among the pan-cancers." (PMID 35247251, 2022). "This suggests that the detection of ABCA10 gene expression in breast cancer tissue has important clinical significance." (PMID 35247251, 2022). "We have used bioinformatic analysis of the TCGA pan-cancer dataset to show that only breast cancer has significantly lower ABCA10 levels than normal tissue." (PMID 35247251, 2022). "We found that ABCA10 expression was downregulated in different subgroups of breast cancer and strongly correlated with pathological stage in BRCA patients." (PMID 35247251, 2022). "Using the Oncomine dataset, we analyzed the levels of ABCA10 in normal breast tissue, breast phyllodes tumor, Intraductal Cribriform breast cancer, mucinous breast cancer, Invasive breast cancer, and other breast cancers." (PMID 35247251, 2022). "In this study, we identified ABCA10 as an oncogenic predictor of breast cancer and tumor immune infiltration." (PMID 35247251, 2022). "We found that the scores of Lypressin and ABCA10 KD on breast cancer cells (MCF7) were 0.39 and 0.27, respectively, indicating a positive correlation between the average transcriptional effect of ABCA10 expression and Lypressin drug activity." (PMID 35247251, 2022). "We further analyzed the dependence of 84 breast cancer cell lines on ABCA10 and mapped the ABCA10 dependence (fold change in sgRNA abundance relative to control transfected cells) of breast cancer cell lines and different subtypes, which were ranked by increasing ABCA10 dependence." (PMID 35247251, 2022). "We found that deletion or amplification of other forms of ABCA10 compared to normal copy number may differentially modulate immune cell infiltration in breast cancer." (PMID 35247251, 2022). "Overall, this study provides evidence that ABCA10 could become the potential targets for precision treatment and new biomarkers in the prognosis of breast cancer." (PMID 35247251, 2022). "We further confirmed the mRNA levels of ABCA10 in breast cancer cells and normal breast cells (H-184B5F5/M10), and the results were consistent with the database data, where ABCA10 levels were significantly higher in normal breast cells than in other breast cancer cells." (PMID 35247251, 2022).
breast carcinoma (continued). "However, there are no reports of low expression and mutation of ABCA10 leading to the progression of breast cancer." (PMID 35247251, 2022). "Therefore, we hypothesize that the immune microenvironment plays a critical role in the development of breast cancer tumors and in the regulation of ABCA10." (PMID 35247251, 2022). "Conversely, genes on chromosome 17 region “Nikolsky Breast Cancer 17q21-q25” were amplified in CR and contained ATP-binding cassette (ABC) transporters (ABCA5/ABCA6/ABCA8/ABCA9/ABCA10) among them (172 genes total, FDR = 7.39E−178)." (PMID 37012431, 2023). "The expression levels of ABCA10 in luminal A, luminal B, basal-like, and HER2 were all lower than normal tissues in different subtypes of breast cancer." (PMID 35247251, 2022). "The role of ABCA10 gene in breast cancer has not been reported." (PMID 35247251, 2022).
ovarian carcinoma (3 papers, 2019 to 2025). A malignant neoplasm originating from the surface ovarian epithelium. "Their study illustrated that ABCA10 facilitates lipid metabolism reprogramming by promoting mitochondrial cholesterol efflux, thereby increasing the sensitivity of ovarian cancer cells to cisplatin (DDP)." (PMID 40445912, 2025). "ABCA10 has been proposed as a prognostic marker in ovarian carcinoma." (PMID 33579221, 2021).
follicular lymphoma (1 paper, 2021). Follicular lymphoma is a form of non-Hodgkin lymphoma characterized by a proliferation of B cells whose nodular structure of follicular architecture is preserved. "Germline single nucleotide polymorphisms in ABCA10 may affect follicular lymphoma overall survival." (PMID 33579221, 2021).
lung disorder (1 paper, 2022). A disease involving the lung. "ABCA3 has been pathologically linked to surfactant deficiency, a lung disorder relating to aberrant lipid transport that is fatal in newborns while there is very little knowledge on the physiological and pathological functions of ABCA9 and ABCA10." (PMID 36385764, 2022).
lymphoma (1 paper, 2014). A malignant (clonal) proliferation of B- lymphocytes or T- lymphocytes which involves the lymph nodes, bone marrow and/or extranodal sites. "The strongest association with lymphoma-specific death was observed at rs10491178 (HRrandom = 3.17, 95% CI 2.09-4.79, prandom = 5.24 × 10−8), located on 17q24 in the ATP binding cassette A10 gene (ABCA10)." (PMID 25294155, 2014). "The increased rate of lymphoma-specific death for carriers of the A allele of rs10491178 in ABCA10 on 17p24 was consistent in the SCALE and UCSF cohorts, strengthening the notion of a possible causal association with this region." (PMID 25294155, 2014). "In the present GWAS meta-analysis, there was suggestive evidence that inherited polymorphisms in the ABCA10 or ABCA6 genes may be associated with risk of lymphoma-specific death." (PMID 25294155, 2014).
metastasis (1 paper, 2023). The spread or migration of cancer cells from one part of the body (where they first appeared) to another.
prostatic tumor (1 paper, 2015). "In addition to ABCA11, the extra-prostatic tumor stage (pT3 vs pT2) was associated with the down-regulation of other ABC transporter genes from subfamily A: ABCA5 (FC 1.73; p = 0.022), ABCA6 (FC 2.00; p = 0.046), and ABCA10 (FC 3.29; p = 0.006)." (PMID 26459268, 2015).
type 2 diabetes (1 paper, 2022). "A gene-level analysis reported in the Metabolic Diseases Knowledge Portal showed associations at ABCA10 with triglycerides, PHIP with fasting insulinadjBMI and type 2 diabetes, and SPTY2D1 with type 2 diabetes." (PMID 35665752, 2022).
tumor (6 papers, 2021 to 2025). "Furthermore, immunotherapy responses and immune infiltration across a variety of tumor types are associated with the expression levels of both ABCA10 and ABCB5." (PMID 40445912, 2025). "ABCA10 is a member of the active transmembrane transport family, and was recently implicated in the progression-free survival of epithelial ovarian sarcoma, and appears to portray a tumor-suppressor role in the context of our findings." (PMID 41048341, 2025). "The tumor-suppressive potential of ABCA10 is further supported by its positive correlation with immune cells." (PMID 40445912, 2025). "ABCA10 appears to exert tumor-suppressive effects through its role in mitochondrial cholesterol efflux and modulation of lipid metabolism, which are essential for maintaining cellular homeostasis." (PMID 40445912, 2025). "We analyzed the expression levels of ABCA10 in normal and tumor tissues of the breast and showed a significant decrease in ABCA10 expression in tumor tissues." (PMID 35247251, 2022). "In this study, we observed the difference of ABCA10 gene expression in normal tissues and tumor tissues by means of big data analysis." (PMID 35247251, 2022). "We used bioinformatic prediction to initially screen out ABCA10, a gene differentially expressed between tumor and normal tissue, for further study and screening of potential drugs." (PMID 35247251, 2022). "To further confirm the accuracy of the multi-omics analysis, we evaluated ABCA10 detected using immunohistochemistry in tumor tissues using 60 BRCA commercial tissue microarray (TMA)." (PMID 35247251, 2022). "The relationship between ABCA10 and various tumor-infiltrating immune cells was evaluated by different immune databases." (PMID 35247251, 2022). "Our study also demonstrated the potential role of ABCA10 modifications in tumor microenvironment (TME) cellular infiltration." (PMID 35247251, 2022). "It is worth mentioning that the expression of ABCA10 has decreased significantly from the early stage, and the level of ABCA10 was the same in different tumor stages of BRCA." (PMID 35247251, 2022). "The differential expression of these genes reveals their possible involvement in different aspects of tumor biology, suggesting that ABCA10 and ABCB5 may play distinct and opposing roles in cancer development and progression." (PMID 40445912, 2025). "Furthermore, ABCA10 expression in BRCA, STAD, and TGCT was significantly positively correlated with cancer-associated fibroblasts, which play a role in tumor development." (PMID 40445912, 2025). "Furthermore, the correlation between ABCA10 and immunosuppressive gene expression suggests that ABCA10 plays a key role in regulating tumor immunology." (PMID 35247251, 2022). "Therefore, the identification of ABCA10 regulators may be a novel strategy to initiate the tumor environment to kill tumors." (PMID 35247251, 2022). "This study presents a unique contribution as the first comprehensive pan-cancer analysis of ABCA10 and ABCB5, highlighting their roles in tumor biology and clinical outcomes." (PMID 40445912, 2025). "Using the median values of ABCA10 and ABCB5 gene expression, tumor cell lines were classified into groups with elevated and reduced expression levels, to obtain DEGs." (PMID 40445912, 2025). "This multidimensional analysis reveals that ABCA10 and ABCB5 play distinct and opposing roles in tumor biology, providing valuable insights into their potential as prognostic biomarkers and therapeutic targets." (PMID 40445912, 2025). "The first in-depth pan-cancer analysis of ABCA10 and ABCB5 is presented in this study, offering valuable insights into their diverse roles in tumor biology." (PMID 40445912, 2025). "Our analysis demonstrated that the expression of ABCA10 was reduced in most tumors, including LUAD and BRCA, supporting its function as a potential tumor suppressor." (PMID 40445912, 2025).
tumor (continued). "The distinct and opposing roles of ABCA10 and ABCB5 may reflect a complex interplay between tumor suppressive and oncogenic forces, necessitating further research to delineate their context-specific functions." (PMID 40445912, 2025). "Next, we examined the mRNA expression of ABCA10 in 30 paired BRCA and non-tumor tissues." (PMID 35247251, 2022).
cancer (4 papers, 2017 to 2025). A tumor composed of atypical neoplastic, often pleomorphic cells that invade other tissues. "Specifically, our findings demonstrated that reduced ABCA10 expression level is linked with worse survival outcomes in several cancers." (PMID 40445912, 2025). "We analyzed the effect of ABCA10 mutations on immune cell infiltration by pan-cancer type and the effect of immune cell type on pan-cancer by mutation module." (PMID 35247251, 2022). "Then the effect of ABCA10 mutations on immune cell infiltration in various cancer types was analyzed by mutation modules in Pan-cancer." (PMID 35247251, 2022). "We found that 7% of ABCA10 genes were mutated in various cancers." (PMID 35247251, 2022). "We found a high rate of ABCA10 gene amplification in pan-cancer, however, gene amplification is an increase in the difference between a specific part of the genome compared to the rest of the genome." (PMID 35247251, 2022). "Next, we used the cBioPortal database to evaluate the type and frequency of ABCA10 alterations in BRCA tissues based on sequencing data from BRCA patients obtained from TCGA’s Pan-Cancer Atlas database." (PMID 35247251, 2022). "Notably, significant correlation was observed between ABCA10 expression and clinical outcome in 10 cancer types, and between ABCB5 expression and prognosis in 6 cancer types." (PMID 40445912, 2025). "Furthermore, the apparent correlation of ABCA10 and ABCB5 with cancer-associated fibroblasts across tumors highlights their broader influence on TIME." (PMID 40445912, 2025). "We observed the gene expression levels of ABCA10 master regulators in pan-cancer." (PMID 35247251, 2022). "Our in-depth bioinformatics exploration highlights the pivotal roles of ABCA10 and ABCB5 genes across a spectrum of cancers, offering insights into potential cancer biomarkers." (PMID 40445912, 2025). "We utilized an innovative bioinformatics approach to bridge this significant gap by simultaneously examining ABCA10 and ABCB5 across multiple cancer types." (PMID 40445912, 2025). "Our research demonstrated that ABCA10 shows reduced expression, while ABCB5 displays variable expression patterns across tumors, indicating their opposing roles and flexible functions in pan-cancer." (PMID 40445912, 2025). "Unlike ABCA10, multiple studies have demonstrated the overexpression of ABCB5 across various cancer types, highlighting its significant role in promoting chemoresistance." (PMID 40445912, 2025). "Following a comprehensive literature review, ATP binding cassette subfamily A member 10 (ABCA10) and ATP binding cassette subfamily B member 5 (ABCB5) were selected as key candidates for downstream analysis due to the absence of systematic pan-cancer analysis of these genes." (PMID 40445912, 2025).
ABCA10 also shares sentences with these, for which no sentence is quoted: acute myeloid leukemia (1 paper); atherosclerosis (1); B-cell lymphomas (1); brain tumors (1); breast phyllodes tumor (1); cardiovascular disease (1); frontotemporal dementia (1); gastric cancer (1); gingival hyperplasia (1); invasive breast carcinoma (1); metabolic disease (1); osteosarcoma (1).